VWF (von Willebrand factor)
Diseases named in the same sentence as VWF in open-access papers (continued):
Sharing a sentence is not in itself a finding about the gene and the disease.
diabetes (continued). "Increased VWF levels and lower ADAMTS13 activity in dialysis patients as compared with the general population could be a reflection of a high prevalence of comorbidities, including cardiovascular diseases and diabetes mellitus." (PMID 34134634, 2021). "Using this assay, elevated active VWF levels were identified in plasma from patients with VWD type 2B, TTP, HELLP syndrome, systemic inflammatory response syndrome, antiphospholipid syndrome, diabetes, first ST-segment elevation myocardial infarction (STEMI), sickle cell disease, malaria and dengue." (PMID 30759116, 2019). "Consistent with these, our co-localization of vWF and TUNEL data suggested a potential involvement of apelin gene therapy on cardiomyocyte apoptosis, but not EC in ischaemic heart of diabetes." (PMID 25311234, 2015). "As the association between ADAMTS13 and diabetes did not appear to be explained by its cleavage of VWF, ADAMTS13 may have an independent role in the development of diabetes." (PMID 27787621, 2017). "Similarly, common comorbidities frequently observed in our patient population, including smoking, hypertension, diabetes mellitus, chronic pulmonary disease (CPD), extracardiac arteriopathy (ECA), and renal function impairment did not appear to significantly affect VWF dynamics." (PMID 39202676, 2024).
coagulopathy (112 papers, 2011 to 2026). "In this review, we have aimed to discuss the age-related increase in VWF, its potential mechanisms, and associated coagulopathies as probable consequences." (PMID 34575297, 2021). "Covering of the ET by HES can limit VWF secretion from the ET and cause coagulopathy by reducing VWF Ag levels." (PMID 34021192, 2021). "Regarding trauma, in a pediatric study, ADAMTS13 decreased with vWF elevation, which was associated with coagulopathy and endothelial cell injury." (PMID 33712048, 2021). "Considering the central role of VWF in hemostasis and thrombosis, both decreased and increased levels of VWF (outside the normal range) are associated with coagulopathies." (PMID 34575297, 2021). "Decreased vWF secretion is also one of the reasons why HPS6 deficiency leads to coagulation disorders." (PMID 35252216, 2021). "In adult patients with ALL, NHL or CLL, ICANS was associated with elevations in serum VWF and IL-8, as well as thrombocytopenia, elevated D-dimer, and decreased fibrinogen levels, all indicative of coagulopathy." (PMID 33391257, 2020). "This increases the risk for developing symptoms of a blood coagulation disorder due to the reduced von Willebrand factor concentrations." (PMID 31131110, 2019). "The mouse model of extracellular histone-induced injury is characterized by endothelial damage and excessive coagulation activation, with increased concentrations of tissue factor (TF) and von Willebrand factor (vWf), bearing a strong resemblance to sepsis-associated coagulopathy." (PMID 37988072, 2024). "Morespecifically, during the inflammatory process, various prothrombotic mediatorssuch as von Willebrand Factor (vWF) are released from the dysfunctionalendothelial cells that appear to play an important role in the establishment ofCOVID-19 associated coagulopathy." (PMID 39077423, 2023). "This prompted us to include vWF parameters and platelet aggregometry into our analysis, hypothesizing that the pathomechanism of abnormal blood flow causing a coagulopathy in patients with external devices may also be observed in vascular anomalies." (PMID 36551267, 2022). "In addition to TF, most other EV‐linked coagulopathy markers, including vWF, uPAR and ADAMTS13, also correlated with D‐dimer, length of hospitalization and age in both LEVs and SEVs." (PMID 34262673, 2021). "VWF is considered to be involved in coagulopathy and thromboembolic disease associated with trauma." (PMID 33939120, 2021). "Unexpectedly, we discovered that M. domestica VWF resists elongation until exposed to much higher shear than human VWF—a striking physiological shift with implications for both venom resistance and human coagulopathies." (PMID 40463117, 2025). "In SIC, PCT stimulates von Willebrand factor release and microthrombosis, exacerbating coagulation disorders." (PMID 40995081, 2025). "An alternative approach, cryoprecipitate, provides supplementary clotting factors, such as Factor VIII and von Willebrand factor (vWF), potentially benefiting patients with multifactorial coagulopathies." (PMID 39941103, 2025). "A subsequent coagulopathy workup, including assays for vWF activity, vWF antigen, FVII, factor VIII, factor IX, and fibrinogen, revealed a FVII level of <1%." (PMID 40760504, 2025). "In SIC, elevated PCT stimulates the release of von Willebrand factor from the vascular endothelium, which promotes microthrombosis and exacerbates coagulation disorders." (PMID 40098952, 2025). "This coagulation disorder, characterized by bleeding due to defects in von Willebrand factor (VWF), plays a crucial role in platelet adhesion to exposed subendothelial collagen at sites of vascular injury." (PMID 39704451, 2025). "It has been reported that VWF not only acts importantly in trauma haemostasis but also in secondary inflammation and coagulation disorders." (PMID 36760352, 2023).
coagulopathy (continued). "Moreover, high levels of glucocorticoids have been shown to elevate levels of von Willebrand factor (vWF), anti-hemophilic factor, fibrinogen, plasminogen activator inhibitor-1, and platelet count, which can result in embolic disorder and further increase the risk of the coagulative disorder." (PMID 37106862, 2023). "In another study, PT, APTT, Von Willebrand factor levels, clotting factor levels and D-dimers demonstrated a mild coagulopathy in all 80 patients evaluated, while WBCT20 was positive in only one patient." (PMID 36588149, 2023). "Non-COVID-19 studies have suggested a corticosteroid associated coagulopathy due to high levels of Factor VIII, Factor IX, and von Willebrand factor (vWF) and enhanced thrombin generation." (PMID 34986821, 2022). "The coagulation abnormalities induced by LPS are similar with previous studies on sepsis-induced coagulopathy, including activation of the endothelium and increased secretion of vWf, resulting in activation of platelets." (PMID 33896590, 2021). "Here we evaluate VWF/ADAMTS13 axis changes that suggest an early endothelial-based coagulopathy along with imbalanced plasma thrombin and plasmin generation." (PMID 35087853, 2021). "Most biomarkers are related to the immune system (SAA,TNF-∝, and IP-10) or coagulopathies (D-dimer, antithrombin, and VWF) and a few have already been established as cancer biomarkers (ACE2, IL-6, IL-4 and IL-2)." (PMID 32935101, 2020). "Coagulopathy in Heyde’s syndrome is expected to abate when AS is treated and destruction of high-molecular-weight vWF multimers stops." (PMID 32026002, 2019). "The first panels offered for clinical diagnosis were small – three genes (F8, F9 and VWF) for a coagulation disorder, for example – in essence just a few single gene tests done together." (PMID 28222731, 2017). "The diagnosis was set by a specialist in coagulations disorders based on clinical data and low values of VWF:RCo." (PMID 26977273, 2016). "These receptors, together with the genes for VWF and Factor XIII, which were also down-regulated in this study, most likely play a role in the coagulopathies and hemodynamics associated with CIRS-ciguatera." (PMID 25889530, 2015). "First and foremost, in the present study, we established strict inclusion and exclusion criteria to ensure that patients with congenital vWF deficiencies or other coagulation disorders were not included." (PMID 40135640, 2025). "Diagnosis relies on specific von Willebrand factor tests, and management requires a multidisciplinary approach, involving cardiology for valve replacement, gastroenterology for lesion treatment, and hematology for coagulopathy correction." (PMID 39803034, 2024). "It is known that vWF activity is increased in cancer patients, which might explain the higher incidence of coagulopathies in these patients." (PMID 36769870, 2023). "We hypothesized that, with its origin in endothelial cells, the vWF may play a central role in coagulopathies in vascular anomalies." (PMID 36551267, 2022). "Von Willebrand factor (vWF) is another factor involved in SARS-CoV-2 coagulopathy." (PMID 35907817, 2022). "Other coagulopathies found were hypofibrinogenemia (15.2%), low VWF activity (11.1%; 2 patients with blood type O positive and 2 patients with A positive), factor XIII deficiency (6.7%), prolonged aPTT (10.5%), prolonged PFA-ADP (8.5%) and prolonged PFA-EPI (10.2%)." (PMID 35213601, 2022). "Coagulopathy, characterized by elevated von Willebrand factor, fibrinogen, and D‐dimers and leading to excessive thrombin production, inhibition of fibrinolysis, and complement activation, has been associated with infection‐mediated endothelialitis and endothelial injury." (PMID 35833542, 2022).
coagulopathy (continued). "Patients with COVID-19 also share similar coagulation markers as other forms of coagulopathy, such as disseminated intravascular coagulation and sepsis-induced coagulopathy, with elevated D-dimer, fibrinogen, prothrombin time, von Willebrand factor, as well as reduced thrombocytes." (PMID 34659238, 2021). "Markedly increased activity of FVIII and overexpressed VWF/ULVWF in patients presenting with EA-VMTD (e.g., TTP-like syndrome) have been mistakenly interpreted to be “hypercoagulable state” or “thrombophilic state” that causes thrombosis or coagulopathy." (PMID 33061857, 2020). "However, the cases with “DIC” always presented with markedly increased FVIII, increased expression of ULVWF/VWF and increased fibrinogen in early stage and decreased in late stage of coagulopathy, and decreased FVII." (PMID 33061857, 2020). "The present study showed that the ratio of VWF/ADAMTS13 increased significantly after the AAA surgery, which may indicate increasing risk of prothrombotic coagulation disorder." (PMID 25960882, 2014). "The admission VWF levels were also correlated with the admission PC/FVII levels, implicating that early low VWF levels might be mainly attributed to coagulopathy and predict a poor outcome." (PMID 24034700, 2013). "Unexpectedly, we find that M. domestica VWF requires increased shear force to elongate, a previously unknown aspect of opossum blood physiology that may contribute to venom resistance and may have relevance to human coagulopathies." (PMID 40971373, 2025). "Furthermore, it is known that proinflammatory cytokines such as TNF-α, IL-1β, and IL-6 can alter the coagulation factor system by increasing the production of fibrinogen, Von Willebrand Factor (vWF), Factor VIII, and Factor XII, which increase the risk of coagulopathies." (PMID 38911850, 2024). "Therefore, it seems reasonable that vWF activity might be an important contributor for coagulopathies, specifically in patients undergoing surgery for pancreatic cancer." (PMID 36769870, 2023). "The upregulation of the MAS1 circuit is related to the normal vascular system functioning, and the activation of this axis may result from a vasoprotective response of the glycoproteins, such as GPVI and vWF, involved in thromboembolism, thromboinflammation, and other coagulopathies." (PMID 38414974, 2023). "Based on our results, it is plausible that SARS-CoV-2 infection of LSECs and LECs through L-SIGN leads to endothelial cell activation and secretion of vWF and FVIII into circulation, which may synergize with ACE2-mediated infection to cause coagulopathy in humans." (PMID 34291736, 2021). "This causal relationship may explain the lower admission VWF levels in patients with than without coagulopathy." (PMID 24034700, 2013). "Therefore, the aim of our study was to investigate whether correlations exist among levels of sPsel, VWF, and coagulation parameters; the presence of coagulopathy; and 30-day mortality among trauma patients." (PMID 24034700, 2013). "In severely injured trauma patients in the ICU, lower levels of sPsel and VWF on admission were associated with the presence of coagulopathy and might not predict a better outcome." (PMID 24034700, 2013). "A comprehensive coagulopathy panel was initiated to evaluate factors VIII, IX, and von Willebrand factor (vWF)." (PMID 41458817, 2025). "Taken together, this study uncovered the involvement of a circ_0001274/miR-143-3p/VWF regulatory network in the occurrence of ATC and suggested the promising protective role of circ_0001274 against coagulation disorders." (PMID 36760352, 2023). "The human ABO blood group led to different plasma levels of VWF and factor VIII (FVIII), which contributed to coagulopathy and CV diseases." (PMID 36836590, 2023). "vWF is a carrier of factor (F)-VIII and both vWF and F-VIII increase fibrin generation and coagulopathy." (PMID 37628764, 2023).
coagulopathy (continued). "Screening for coagulation disorders revealed the factor VIII and von Willebrand factor (vWF) values were low, at 47.6 and 23%, respectively." (PMID 35151252, 2022). "Coagulopathy, including elevated D-dimer levels, prolonged prothrombin time, decreased platelet counts, elevated PAI-1 and Von Willebrand factor (VWF) have been highlighted in severe cases." (PMID 36128671, 2022). "Screening for coagulation disorders revealed that the patient’s factor VIII and von Willebrand factor (vWF) values were low at 47.6 and 23%, respectively." (PMID 35151252, 2022). "Using a controlled cortical impact mouse model, we demonstrated that the acrolein scavenger phenelzine prevented TBI-induced coagulopathy and recombinant ADAMTS-13 prevented acrolein-induced coagulopathy by cleaving von Willebrand factor (VWF)." (PMID 33939120, 2021). "An extremely interesting finding in acute hepatitis patients with severe hepatic coagulopathy, acute liver failure and fulminant hepatic failure has shown markedly increased FVIII activity and increased expression of VWF." (PMID 33061857, 2020). "vWF activity also improved from 51% to 142%; AVR had improved not only the hemodynamic status but also coagulopathy." (PMID 30448636, 2018). "In an early phase of trauma, VWF levels in patients with coagulopathy were lower than those in patients without coagulopathy." (PMID 40507007, 2025). "The admission VWF levels were also correlated with the admission PC/FVII levels, implying that early low VWF levels might be mainly attributed to coagulopathy probably related to an impairment of thrombin generation." (PMID 40507007, 2025). "The P‐selection and vWF were expressed in the initial phase of coagulopathy, unlike the PLAT, PAI‐1, and TF, which were upregulated in the late phase (fibrinolytic system)." (PMID 38098255, 2024). "In our study, the admission VWF levels in patients with coagulopathy and in nonsurvivors were lower than those in patients without coagulopathy and survivors." (PMID 24034700, 2013). "Both the admission sPsel and VWF levels were lower in patients with coagulopathy than in those without (p < 0.05) and were significantly correlated with the protein C and factor VII levels, respectively (all p < 0.05)." (PMID 24034700, 2013). "Unexpectedly, we find that M. domestica von Willebrand Factor (VWF) requires increased shear force to elongate, a previously unknown aspect of opossum blood physiology that may contribute to venom resistance and may have relevance to human coagulopathies." (PMID 40463117, 2025). "Second, we did not assess the levels of vWF and its multimer which directly affects coagulation associated with ADAMTS13 in this study, so we need to examine them to clarify the pathogenesis of the association between ADAMTS13 and trauma-induced coagulopathy." (PMID 33712048, 2021).
atherosclerosis (110 papers, 2009 to 2026). A disease characterized by the build-up of fatty material and calcium deposition in the arterial wall resulting in partial or complete occlusion of the arterial lumen. "Elevated von Willebrand factor (VWF) levels correlate with higher risk of atherosclerosis-related arterial thrombosis (atherothrombosis)." (PMID 40093962, 2025). "Sustained increases in endothelial surface-associated von Willebrand factor (VWF) and secondary platelet adhesion beyond that which occurs during indolent atherosclerosis has also been detected on arterial molecular imaging." (PMID 38693516, 2024). "Together with fibrinogen, VWF is involved in platelet aggregation and plays a role in the development of atherosclerosis, which is associated with a high risk of heart ischemia and thromboembolic disease." (PMID 38890319, 2024). "VWF is known to contribute to atherosclerosis and is associated with an increased risk of coronary heart disease and ischemic stroke." (PMID 37375810, 2023). "Although decreased ADAMTS13 activity and increased VWF level increase the risk of atherosclerosis, most scholars believe that ADAMTS13 and VWF level were two independent risk factors." (PMID 34276770, 2021). "VWF traps platelets in atherosclerosis-prone sites via binding to its platelet receptor glycoprotein Ib domain, and VWF deficient mice have reduced atherosclerosis." (PMID 32273567, 2020). "vWF involves the adhesion of platelets to endothelial cells, which is associated with the formation of thrombus and atherosclerosis." (PMID 32384920, 2020). "The von Willebrand factor (vWF) is a further factor that is implicated in the pathogenesis of atherosclerosis." (PMID 32408603, 2020). "In a 5-year follow-up of 1592 persons 55–74 years old, smoking was associated with higher levels of vWF and a higher risk of atherosclerosis development." (PMID 33096906, 2020). "The VWF/ADAMTS13 axis is implicated in the pathogenesis of atherosclerosis, promoting plaque formation and inflammation through macrophage and neutrophil recruitment in inflamed lesions." (PMID 28634421, 2017). "It has been shown that VWF deficiency or loss of function has a protective effect on atherosclerosis." (PMID 27889498, 2016). "We demonstrated association of vWF activity and subclinical atherosclerosis in low-risk RA patients as well as its correlation with inflammation markers, all parameters of disease activity, and seropositivity." (PMID 26247590, 2015). "Higher levels of factor VIII and vWF lead to increased thrombotic tendency, and plasma cholesterol is a known risk factor for atherosclerosis." (PMID 25592833, 2015). "We also found highly significant correlation of vWF activity with age in RA patients, which was probably the reason for the loss of independent predictive value of vWF activity for subclinical atherosclerosis in multiple regression models." (PMID 26247590, 2015). "Furthermore, animal studies have shown that decreased VWF levels are associated with slower progression of atherosclerosis, which is in turn associated with a reduced risk of thrombosis." (PMID 39726607, 2024). "Another component that has been associated with atherosclerosis is the von Willebrand factor." (PMID 36553147, 2022). "Of note, vWF up-regulation is often associated with endothelial damage and inflammation, platelet aggregation, and adhesion, and it is considered as a biomarker of atherosclerosis and thrombogenesis, among others." (PMID 35624715, 2022). "vWF is considered a risk factor of arterial thrombosis and might contribute to the development of adverse events in atherosclerosis and other cardiovascular diseases." (PMID 33096906, 2020). "In summary, CC, macrophages, C1q and vWF have all been implicated in atherosclerosis." (PMID 31824501, 2019). "A possible pathogenic role of VWF/ADAMTS‐13 in atherosclerosis has also been suggested." (PMID 29108103, 2018).